TF (transferrin)
Diseases named in the same sentence as TF in open-access papers (continued):
Sharing a sentence is not in itself a finding about the gene and the disease.
metabolic syndrome (18 papers, 2006 to 2026). A cluster of metabolic risk factors for CARDIOVASCULAR DISEASES and TYPE 2 DIABETES MELLITUS. "While high egg intake has been linked to increased mortality and dyslipidemia, eggs contain compounds like Ovo transferrin and carotenoids that may benefit bone health." (PMID 38696440, 2024). "Those patients who met the criteria for the metabolic syndrome had slightly higher ferritin and C-peptide values, but lower transferrin saturation than the rest of the study population." (PMID 18958176, 2008). "Adipose tissue inflammation and hepatokine dysregulation may further disrupt iron metabolism, amplifying transferrin elevation in the context of metabolic syndrome." (PMID 41211637, 2025).
alcohol abuse (17 papers, 2003 to 2026). The use of alcoholic beverages to excess, either on individual occasions ("binge drinking") or as a regular practice. "Carbohydrate-deficient transferrin (CDT) is mainly known as a long-term marker for alcohol abuse and describes transferrin isoforms which are deficient in their structure and appear after ethanol consumption of about 50–80 g/d for more than 10–15 days." (PMID 40301838, 2025). "Another early example of a glycoprotein with value for clinical diagnostics is transferrin, be it for the assessment of alcohol abuse through carbohydrate-deficient transferrin or for the diagnosis of CDGs." (PMID 37169080, 2023). "Carbohydrate deficient transferrin (CDT) is a liver-produced variant of serum transferrin that indicates chronic heavy alcohol abuse with adequate accuracy." (PMID 37854697, 2023). "Genetically predicted alcohol use disorder was associated with serum iron and transferrin saturation." (PMID 35834561, 2022). "Carbohydrate deficient transferrin is routinely measured for alcohol abuse using immunonephelometric or immunoturbidimetric techniques, but MS-based methods have been reported to characterize reference materials and calibrators." (PMID 34820521, 2020). "Carbohydrate-deficient transferrin (CDT) is a highly specific biomarker for the detection of chronic alcohol abuse." (PMID 31159489, 2019). "Carbohydrate-deficient transferrin (CDT) is one of the most used biomarkers of chronic alcohol abuse, mainly because of its high specificity." (PMID 31192254, 2019). "Untreated hereditary fructosemia and galactosemia, alcohol abuse, hepatopathy, and bacterial sialidases are known as secondary causes of abnormal transferrin glycosylation." (PMID 29497882, 2018). "The blood protein known as carbohydrate-deficient transferrin frequently is used to detect current or recent alcohol abuse, especially consumption in excess of 60 grams per day, but there are no ideal tests to identify continuing alcohol intake." (PMID 15535453, 2003). "Additionally, carbohydrate-deficient transferrin (CDT) as an established marker of alcohol abuse was evaluated in these patients." (PMID 31192254, 2019). "Regarding alcohol abuse, beyond liver enzymes and MCV, carbohydrate-deficient-transferrin (CDT) and phosphatidylethanol (PEth) levels can be measured if chronic alcohol abuse is suspected and not admitted." (PMID 41602963, 2026). "Human plasma transferrin (Tf) N-glycosylation has been mostly studied as a marker for congenital disorders of glycosylation, alcohol abuse, and hepatocellular carcinoma." (PMID 36959410, 2023). "Whilst desialylated transferrin is a fairly new marker of alcohol abuse, its usefulness in diagnostics is increasing." (PMID 36983134, 2023). "The most advanced example of clinical glycomics by MS is the analysis of transferrin glycosylation in the diagnosis of alcohol abuse and CDGs." (PMID 34820521, 2020). "However, for two glycoproteins, glycosylation is included as a biomarker in routine clinical diagnostics, namely carbohydrate-deficient transferrin for the detection of CDG and alcohol abuse, and fucosylated serum alpha-fetoprotein (AFP-L3) for the early diagnosis of hepatocellular carcinoma." (PMID 29497882, 2018). "Alcohol abuse biological markers include gamma-glutamyl transferase (GGT), aspartate aminotransferase (AST), alanine aminotransferase (ALT), mean corpuscular volume (MCV), and the low-carbohydrate isoform of transferrin (CDT), or desialated transferrin." (PMID 36834108, 2023). "One study utilized the NHANES III data (1988–1994) and defined NAFLD as subjects with elevated serum aminotransferases in the absence of alcohol abuse, elevated transferrin saturation, and positivity for viral hepatitis." (PMID 28346543, 2017).
endometriosis (17 papers, 2018 to 2025). The growth of functional endometrial tissue in anatomic sites outside the uterine body. "Excess iron and transferrin deficiency were both identified in the follicular fluid of women with both infertility and endometriosis." (PMID 37296777, 2023). "Follicular fluid from women with endometriosis caused a significantly lower in vitro oocyte maturation rate compared to fluid from controls, and the addition of transferrin to bind excess iron proved reversibility, demonstrated by an improved maturation rate." (PMID 37638130, 2023). "A total of 110 target genes, 7 TF genes, and 4 lncRNAs associated with miR-200b-3p were identified in endometriosis." (PMID 32802844, 2020). "Endometriosis-associated infertility may be due to a significant reduction in TF with iron overload resulting in oocyte immaturity." (PMID 39176081, 2024). "Visualizing the core regulatory network in the TF-miRNA core regulation network helps identify key miRNAs influencing the prognosis of endometriosis." (PMID 39650066, 2024). "Comprehensive analysis of the PPI network, TF-miRNA core regulatory network provides valuable information for understanding the regulatory mechanisms and potential therapeutic targets of endometriosis and its progression." (PMID 39650066, 2024). "The concentration of follicular fluid transferrin decreased in women with endometriosis-related infertility." (PMID 37296777, 2023). "Significantly higher levels of follicular free iron and ferric iron in addition to lower transferrin levels with transferrin saturation all indicated ‘iron overload’ in women with endometriosis compared to those with tubal infertility." (PMID 37638130, 2023). "In endometriosis PF, more transferrin is bound by iron, as confirmed by higher transferrin saturation." (PMID 34782602, 2021). "To determine the level of iron in endometriosis PF, we measured the iron, transferrin, and ferritin concentrations in the PF supernatant and calculated the transferrin saturations." (PMID 34782602, 2021). "In this work, a multifunctional co-expression network was constructed among lncRNA, miRNA, mRNA, and TF to investigate the mechanism of endometriosis." (PMID 34790699, 2021). "Immunohistochemical studies revealed a marked elevation of TF expression pattern in eutopic and ectopic endometrium from women with endometriosis." (PMID 32784640, 2020). "Given PT is initiated by TF, our findings correspond to previous studies that have reported the elevation of TF in endometriotic lesions and PF in women with endometriosis." (PMID 31888633, 2019). "In a mouse model of endometriosis, a chimeric immunoconjugate molecule specifically targeting endothelial TF in ectopic implants has been shown to obliterate the endometriotic implant by vascular disruption without reducing fertility." (PMID 31888633, 2019). "In plasma, lactoferrin showeds associations with iron and transferrin in endometriosis and with ferritin in the group without endometriosis." (PMID 36675136, 2023). "Iron overload and transferrin insufficiency induce the excess of ROS, compromising the integrity of the mitotic spindle by promoting chromosome instability, which may affect the number and maturation of oocytes retrieved from women with endometriosis." (PMID 37296777, 2023). "The PF of patients with endometriosis (n = 41) showed significantly higher iron concentrations (16.67 vs. 10.13 μmol/L; P < 0.001), ferritin concentrations (416.6 vs. 79.10 ng/mL; P < 0.001) and transferrin saturation (51.93% vs. 32.25%; P < 0.001) than those of the controls (n = 31)." (PMID 34782602, 2021). "Because transferrin functions as an iron transporter in the human body, a high transferrin level in peritoneal fluid could reflect a high iron level in peritoneal fluid in endometriosis patients." (PMID 30104541, 2018). "Lactoferrin in peritoneal fluid correlated with lactoferrin, iron and transferrin of plasma in patients without endometriosis." (PMID 36675136, 2023).
endometriosis (continued). "LF concentrations in peritoneal fluid correlated with LF, Fe and TF plasma concentrations in the group without endometriosis." (PMID 36675136, 2023). "Tissue factor elevation in women with endometriosis is thought to explain symptoms of dysmenorrhea and HMB, and given the similarities between endometriosis and adenomyosis, the authors proposed to identify elevated TF expression in women with adenomyosis." (PMID 30388215, 2019). "Moreover, tissue factor (TF, coagulation factor III) is also increased in the endometriotic lesions and PF in women with endometriosis." (PMID 31888633, 2019). "The presented results compare, for the first time, the concentrations of acute phase proteins, also known as iron-binding proteins (LF, TF, FT) and the concentration of iron as a panel of parameters measured simultaneously in plasma and peritoneal fluid in patients with and without endometriosis." (PMID 36675136, 2023). "Transferrin concentrations were significantly higher in plasma compared to peritoneal fluid in contrast to ferritin and Fe that were significantly higher in peritoneal fluid, p < 0.05 (only Fe in the group without endometriosis higher, but without statistical significance)." (PMID 36675136, 2023). "Additionally, in vitro studies have shown that endometrial stomal and epithelial cells are able to incorporate TF and metabolize it into FT, and this may be the reason why TF ratios had similar values in the group without and with endometriosis." (PMID 36675136, 2023).
periodontitis (17 papers, 2007 to 2026). An acute or chronic inflammatory process that affects the tissues that surround and support the teeth. "A Danish study revealed lower salivary levels of NGAL (neutrophil gelatinase-associated lipocalin) and transferrin in psoriatic patients compared with patients with periodontitis and orally healthy controls." (PMID 34209865, 2021). "As a whole, this study supports the association between the iron burden, especially elevated transferrin saturation, and the periodontitis severity." (PMID 30341355, 2018). "Increased transferrin saturation (TSAT) has been associated with severe periodontitis, which is a chronic inflammatory disease affecting tissues surrounding the teeth and is related to dysbiosis of the subgingival microbiota." (PMID 30341355, 2018). "Three months after periodontal treatment, improvements were detected in all the periodontal clinical parameters in association with an increase in transferrin serum levels in patients with chronic periodontitis." (PMID 27651883, 2016). "Nevertheless, we have previously demonstrated significantly different transferrin levels in saliva in patients with periodontitis and healthy controls, which is why these were included in the present study." (PMID 33805894, 2021). "error 320], periodontitis: 2,072, orally healthy controls: 2,551 ng/ml, p < .0001) and transferrin (psoriasis: 4.37 [0.92], periodontitis: 7.25 [0.88], orally healthy controls: 10.02 [0.94] ng/ml, p < .0001) were identified in patients with psoriasis." (PMID 31916654, 2020). "Salivary transferrin levels were also significantly lower in patients with psoriasis (4.37 [0.92] ng/ml), as compared to patients with periodontitis (7.25 [0.88] ng/ml) and orally healthy controls (10.02 [0.94] ng/ ml, p < .0001)." (PMID 31916654, 2020). "We found significantly lower salivary levels of NGAL and transferrin in patients with psoriasis, as compared to patients with periodontitis and orally healthy controls, respectively." (PMID 31916654, 2020). "Non-surgical periodontal treatment resulted in an increase in serum levels of transferrin in chronic periodontitis group, which reached the levels in periodontally healthy subjects." (PMID 27651883, 2016). "Based on the results, the transferrin serum levels in patients with chronic periodontitis were significantly lower than those in periodontally healthy subjects." (PMID 27651883, 2016). "The results of this study showed an inverse relationship between serum transferrin and chronic periodontitis, i.e. lower transferrin serum levels were detected in patients with chronic periodontitis." (PMID 27651883, 2016). "The mean serum transferrin levels in the control and chronic periodontitis groups were 307.8 ± 11.7 and 213.1 ± 9.2 mg/dL, respectively, with significant differences between the two groups." (PMID 27651883, 2016). "All the subjects with chronic periodontitis exhibited significant increases in transferrin serum levels 3 months after periodontal treatment (P < 0.01)." (PMID 27651883, 2016). "Furthermore, specific salivary proteins such as transferrin, human IgG1 heavy chain fragment, and amylase have been related to higher oxidation levels in periodontitis compared to healthy controls." (PMID 40710173, 2025). "The purpose of the present study was to characterize the composition of the salivary microbiota and measure salivary levels of NGAL and transferrin in patients with psoriasis, and compare these data to the characteristics in patients with periodontitis and orally healthy controls." (PMID 31916654, 2020). "Furthermore, patients with psoriasis had significantly lower salivary NGAL and transferrin levels than patients with periodontitis and orally healthy controls." (PMID 31916654, 2020). "Also, salivary transferrin levels were lower in patients with psoriasis compared to patients with periodontitis and orally healthy controls, respectively." (PMID 31916654, 2020).
periodontitis (continued). "One reason for a decrease in serum transferrin in patients with chronic periodontitis compared to the controls might be the effects of chronic inflammation on systemic conditions." (PMID 27651883, 2016). "Based on the observations above, we hypothesized that a decrease in transferrin serum levels might be related to chronic periodontitis and a return to its normal levels can be expected in response to periodontal treatment." (PMID 27651883, 2016). "A study by Shirmohammadi et al39 on the effect of non-surgical periodontal treatment on serum transferrin levels showed that 3 months after treatment, all the clinical periodontal parameters improved in association with an in increase in serum transferrin levels in the chronic periodontitis group." (PMID 35919773, 2018). "In addition, patients with periodontitis had a higher level of hepcidin [SMD = 0.59, CI = (0.05, 1.12)] and decreased level of transferrin [SMD = -4.6, CI = (-13.1, -3.90)], with high heterogeneity." (PMID 32082180, 2020). "Conversely, other reports have shown that serum transferrin levels in HD patients with periodontitis (mean/SD; 211.7/68.2 mg/dL) were similar (p = 0.11) to those without periodontitis (263.8/81.4 mg/dL)." (PMID 31382656, 2019). "The transferrin serum levels were lower in the subjects with chronic periodontitis but the differences between the two groups were not significant." (PMID 27651883, 2016). "However, no study is available on the relationship between transferrin serum levels and chronic periodontitis and non-surgical periodontal treatment in systematically healthy subjects." (PMID 27651883, 2016). "Similarly, our Factor 2 (an indicator of no clinically significant periodontitis) featured a relatively high loading (with a small value of loading factor of 0.02) only in the IgG against PGMX but low loadings in all the other IgGs, including the two IgGs against TF and TD." (PMID 27748442, 2016).
ischemic stroke (16 papers, 2018 to 2026). A stroke disorder caused by obstruction of blood flow to the brain, due to thrombotic (local blood clot formation) or embolic (due to a blood clot or other material traveling from another site) event. "For example, transferrin is produced in the brain, and high transferrin levels have been associated with hypercoagulability and ischemic stroke." (PMID 32751741, 2020). "Following ischemic stroke, compromised blood–brain barrier integrity allows both transferrin-bound iron and free iron to passively diffuse into brain tissue, leading to decreased serum iron levels." (PMID 41601539, 2026). "A 3D-printed electrochemical microfluidic device (3D-EMD) was developed to assess the transferrin saturation (TSAT) biomarker in ischemic stroke patients." (PMID 41451703, 2025). "DFO (40–60 mg/kg/day) significantly reduces serum transferrin saturation in stroke patients and has a positive effect on patients with moderate to severe ischemic stroke." (PMID 39396974, 2024). "After ischemic stroke, the blood–brain barrier is destroyed and excessive Fe3+ in blood is released into the brain parenchyma via transferrin (TF) and TFR1." (PMID 35327620, 2022). "Similar trends for the presence of ischemic stroke were found in men and women from low to high level of TF-UP." (PMID 33633672, 2021). "The median of TF-UP/Alb-UP was also decreased in the ischemic stroke group in a statistically significant manner by single variate analysis (P < 0.0001)." (PMID 33633672, 2021). "The change in serum TF-UP level was statistically and clinically significant in patients with ischemic stroke, compared with the BT-SM group." (PMID 33633672, 2021). "Multivariate logistic regression analysis demonstrated a significant inverse relation between serum TF-UP level and the presence of ischemic stroke (P < 0.0001)." (PMID 33633672, 2021). "Lower serum levels of transferrin have been found in patients with ischemic stroke, compared with healthy subjects." (PMID 33633672, 2021). "In conclusion, serum transferrin, albumin, and prealbumin levels in patients with ischemic stroke may correlate with dysphonia severity as assessed using DSI and MPT." (PMID 36771359, 2023). "In preclinical studies, our laboratory has shown that ATf, the iron-free form of transferrin (Tf), is a potent neuroprotective agent in ischemic stroke because it reduces the saturation of blood transferrin with iron (TSAT) and inhibits the entry of iron-Tf into the neurons." (PMID 38001798, 2023). "Serum transferrin, albumin, and prealbumin levels in patients who have suffered an ischemic stroke may correlate with dysphonia severity as assessed using DSI and MPT." (PMID 36771359, 2023). "However, there are no studies on the association between serum transferrin, albumin, and prealbumin and dysphonia severity in patients who have suffered an ischemic stroke." (PMID 36771359, 2023). "Notably, transferrin may not only contribute to ischemic strokes via inducing coagulation, it may also increase the brain injury associated with hemorrhagic strokes by facilitating cellular iron uptake." (PMID 32751741, 2020). "Upon ischemic stroke, the BBB was disrupted and led to increased iron influx through iron‐loaded TF." (PMID 37480159, 2023).